ICAM1 (intercellular adhesion molecule 1)
Diseases named in the same sentence as ICAM1 in open-access papers (continued):
Sharing a sentence is not in itself a finding about the gene and the disease.
endothelial dysfunction (continued). "In conclusion, the present study reveals that MSCs-CM significantly attenuates endothelial dysfunction against IR injury in the aorta of BD rats, in part, by lowering inflammatory response (through VCAM-1, ICAM-1 expression regression) and reducing caspase-mediated apoptosis." (PMID 33627181, 2021). "Adhesion molecules, including ICAM-1 and VCAM-1, which may indicate endothelial dysfunction, are increased under conditions of high inflammation and oxidative stress." (PMID 34769353, 2021). "Aggravated endothelial inflammation, which is characterized by overexpressed cytokines and adhesion molecules such as intercellular adhesion molecule-1 (ICAM-1), vascular cell adhesion molecule-1 (VCAM-1), and selectins, is an important pathological process in endothelial dysfunction." (PMID 34925018, 2021). "In SIRT6 knockout mice, atherosclerotic plaque was enlarged, plaque vulnerability was enhanced, and the expression of ICAM-1 in aortic endothelial cells was significantly up-regulated, implying that SIRT6 is the primary negative regulator of endothelial dysfunction and atherosclerotic development." (PMID 33855020, 2021). "Also, ICAM-1, VCAM-1 and E-selectin intervene with inflammatory cytokines of the vascular wall to promote extravasations and subsequent endothelial dysfunction." (PMID 32893859, 2020). "Other authors have shown attenuating in vitro effects of urolithin A on endothelial dysfunctions induced by oxidized LDL through the beneficial modulation of TNF-α, IL-6, endothelin 1, PPAR-γ, ICAM-1 (intercellular adhesion molecule 1), and MCP-1 (monocyte chemotactic protein 1) expression." (PMID 33322602, 2020). "Activated endothelial cells produce proinflammatory cytokines (i.e., IL1β, IL6, TNFα), chemokines (i.e., CCL2, CXCL1) and adhesion molecules (i.e., intercellular adhesion molecule 1 -ICAM1-, vascular cell adhesion molecule 1-VCAM1, selectins), which participate in endothelial dysfunction." (PMID 32674367, 2020). "Nitric oxide synthesis could be altered in EDS patients given the recent finding that markers of endothelial dysfunction such as VCAM-1, ICAM-1 and MCP-1 are increased in vEDS patients." (PMID 32933483, 2020). "Furthermore, ICAM-1 and VCAM-1 are characteristic molecules of endothelial dysfunction, which also illustrates the superior effects of BMMSCs for reducing hepatic sinusoidal endothelial and vascular endothelial injury." (PMID 32347385, 2020). "This experimental model demonstrated endothelial dysfunction, manifested by the inflammatory cytokine TNF-α as well as by adhesion molecules that are indicators of endothelial damage, such as ICAM-1 (87.6%, 122 ± 9 vs 65 ± 5, p < 0.0001) and VCAM-1 (29.4% 110 ± 10 vs 85 ± 2, p < 0.05)." (PMID 32795274, 2020). "Likewise, an increased levels of ICAM-1, VCAM-1, and selectins in women with GDM are a reflection of endothelial dysfunction contemplating the future metabolic risks via metabolic memory effects." (PMID 33085688, 2020). "The suppression of both ICAM-1 and VCAM-1 expression by Ginkgolide B indicates that this compound could alleviate Ox-LDL-induced endothelial dysfunction." (PMID 31281844, 2019). "Inflammatory markers (TNF-α, IL-6, hsCRP) and endothelial dysfunction markers (E-selectin, ICAM-1, VCAM-1) between MetS and non-MetS patients by gender." (PMID 31550292, 2019). "This study highlights the involvement of adhesion molecules (VCAM-1, ICAM-1, and E-Selectin) in the endothelial dysfunction of SCD patients with and without complications." (PMID 29690499, 2018). "Levels of TNFα (inflammation) or ICAM-1 and VCAM-1 (endothelial dysfunction) are classically elevated in these conditions and may therefore alter LpPLA2 activity." (PMID 28974763, 2017). "This demonstrates that miR-146a-5p may have therapeutic potential, mitigating endothelial dysfunction through the downregulation of both IRAK-1 and ICAM-1." (PMID 28824448, 2017).
endothelial dysfunction (continued). "Furthermore, the adhesion molecules such as intercellular adhesion molecule-1 (ICAM-1) and lectin-like oxidized low-density lipoprotein receptor-1 (LOX-1) play important roles in endothelial dysfunction and vascular injury." (PMID 26881260, 2016). "That other circulating markers of endothelial dysfunction such as coagulation factor VIII, E-selectin, intercellular adhesion molecule-1, and tPA have also been found to predict T2D10, 33, 34, 35, 36, 37, also supports a role of PAI-1 in the pathogenesis of T2D." (PMID 26813008, 2016). "Markers of endothelial dysfunction, like circulating levels of E-selectin, vascular adhesion molecule-1 (VCAM-1), intercellular adhesion molecule 1 (ICAM-1), as well as inflammatory parameters like CRP and IL-6, have been reported to be associated with CVD in several studies." (PMID 22518122, 2012). "In addition to the previous study, the PPAR-α activator, docosahexaenoic acid (DHA), abrogated the development of hypertension, decreased ICAM-1, VCAM-1, corrected structural abnormalities, and improved the endothelial dysfunction induced by Ang II." (PMID 22848208, 2012). "We know of no study that has directly investigated the role of lead on endothelial dysfunction [i.e., adhesion molecules such as intercellular adhesion molecule-1 (ICAM-1)]." (PMID 22142875, 2012). "No relation was found between resistance artery function and other surrogate markers of endothelial dysfunction (soluble intercellular adhesion molecule-1 (sICAM-1) and sVCAM-1) in ESRD and controls (data not shown)." (PMID 22563439, 2012). "As a complementary approach to evaluate a potential endothelial dysfunction in response to diabetes, the expression of VCAM-1, ICAM-1, P-selectin and E-selectin mRNA was measured in intact retinas of wt, ApoE−/−, TNFα−/− and ApoE−/−/TNFα−/− mice by real time RT-PCR." (PMID 20856927, 2010). "Moreover, further investigation into additional molecular pathways, such as oxidative stress markers, endothelial dysfunction mediators (e.g., VCAM-1, ICAM-1), and cytokine signaling pathways, would help clarify the underlying mechanisms of cigarette smoke-induced vascular injury." (PMID 40138141, 2025). "The first step in atherogenesis involves endothelial dysfunction, characterized by increased permeability, decreased nitric oxide (NO) production, and enhanced expression of adhesion molecules, such as vascular cell adhesion molecule-1 (VCAM-1) and intercellular adhesion molecule-1 (ICAM-1)." (PMID 39596083, 2024). "ICAM-1 and VCAM-1 are expressed on the cell surface and serve as cell adhesion molecules to mediate the transformation of monocytes and eosinophils into vascular endothelial cells, which exist in a soluble form in the plasma and are reliable markers of inflammation and endothelial dysfunction." (PMID 38251031, 2024). "As pulmonary adhesion molecules, ICAM1 and VCAM1, as lung adhesion molecules, bind to the endothelial surface and are involved in leukocyte infiltration through the ECs and into the lungs; their elevation is considered an early event in endothelial dysfunction." (PMID 39493864, 2024). "It was also recently proposed that MOTS-c may also improve endothelial dysfunction via the MAPK/NF-κB pathway, which is involved in endothelial dysfunction by regulating the surface expression of adhesion molecules such as VCAM-1 and ICAM-1." (PMID 36670507, 2023). "However, in the current study, we observed no changes in the expression of ET-1, VCAM1, or ICAM1 in TNFα induced endothelial dysfunction in HUVECs when treated with 10 mU/mL of insulin for 24 h." (PMID 37893034, 2023). "The biomarkers like ICAM-1 and PECAM-1 can be utilized in the detection of these endothelial damages because increased levels of these biomarkers are indicative of chronic inflammation and endothelial dysfunction, which are also the characteristics of the CNS in post-treatment BC patients." (PMID 35268306, 2022).
endothelial dysfunction (continued). "As the endothelial dysfunction ensued, the proinflammatory cytokines may further activate the ECs, hence increasing the expression of adhesion molecules such as VCAM-1, ICAM-1, and even EC-derived MPs (EDMPs) subpopulation such as cluster differentiation 62 (CD62E) or E-selectin." (PMID 33718454, 2021). "The decrease in transpulmonary ICAM-1 and VCAM-1 concentrations in PAH children (fold change 0.86 and 0.85, respectively) indicates either intrapulmonary uptake or increased intrapulmonary degradation of these vascular injury mediators that drive endothelial dysfunction." (PMID 34957265, 2021). "Furthermore, NF-κB target genes present in endothelial cells are adhesion molecules, including intercellular adhesion molecule-1 (ICAM-1), VCAM-1, and E-selectin, which intervene with inflammatory cytokines of the vascular wall to promote extravasations and subsequent endothelial dysfunction." (PMID 32069832, 2020). "Phenolic extracts derived from RB down-regulated the expression of four genes, ICAM1, CD39, CD73 and NOX4 and up-regulated the expression of another four genes, Nrf2, NQO1, HO1 and eNOS, indicating an antioxidant/ anti-inflammatory effect for RB against endothelial dysfunction." (PMID 31547608, 2019). "Endothelial dysfunction can also be evaluated by quantifying specific indicators of coagulation such as plasminogen activator inhibitor-1 (PAI-1), markers of inflammation (e.g. ICAM-1 and VCAM-1, or circulating markers derived from the endothelium such as ADMA (asymmetric dimethylarginine)." (PMID 31456040, 2019). "Thus, we anticipated the level of s-ICAM-1 and s-VCAM-1 would be upregulated following EMPs treatment and may contribute to endothelial dysfunction." (PMID 28114372, 2017). "A few authors have shown that pGDM individuals, despite being currently free from metabolic abnormalities, have higher values of markers of endothelial dysfunction, such as E-selectin and intercellular adhesion molecule 1 or ICAM-1, but there is not a consensus." (PMID 24955136, 2014). "In line with endothelial dysfunction in AA, which may permit enhanced lymphocyte extravasation following IP collapse, we also show increased endothelial ICAM‐1 expression in AA scalp, even at nonlesional sites, and replicate this response in vitro with UA using HFOC." (PMID 41387231, 2025). "However, additional parameters, such as soluble ICAM-1, could also be effective in evaluating endothelial dysfunction via significantly elevated levels in non-survivors compared to survivors and via a positive correlation with fibrinogen." (PMID 38276214, 2024). "Moreover, VCAM-1 but not intercellular adhesion molecule-1 (data not shown), endothelin, or E-selectin were significantly diminished in the group with high miR-126 compared with low miR-126 expression, reflecting less endothelial dysfunction." (PMID 27127202, 2016). "At present, we cannot strictly exclude a rather speculative effect of slight elevations of plasma lipids, oxLDL, or ICAM-1 in SM compared to NSM, because these factors may be associated with endothelial dysfunction, which may not spare out the carotid body arteries." (PMID 27881161, 2016). "Elevated Non-HDL-C also exacerbates endothelial dysfunction by reducing endothelial nitric oxide synthase (eNOS) activity and stimulating expression of adhesion molecules (VCAM-1, ICAM-1), thereby reinforcing the classic LDL-C–endothelial interaction." (PMID 40708721, 2025). "Biomarkers of endothelial dysfunction and low-grade inflammation were not modified (CRP, serum amyloid A, IL-6, IL-8, TNF-α, and soluble intercellular adhesion molecule-1) and neither was FMD." (PMID 31068933, 2019). "Markers of endothelial dysfunction, ICAM-1 and VCAM-1, were both increased in ESRD patients lacking GSTM1, while ICAM-1 was upregulated in endothelial cells with a low level of GSTM1 exposed to uremic serum, further strengthening their potential biomarker role as predictors of CVD in ESRD patients." (PMID 33574979, 2021).
endothelial dysfunction (continued). "Plasma concentrations of E-selectin, ICAM-1, and VCAM-1 as markers of endothelial dysfunction were proven to predict development of T2D in initially nondiabetic women, and the association was independent of other known risk factors such as subclinical inflammation and obesity." (PMID 22474520, 2012).
diabetes (275 papers, 2005 to 2026). "In metabolic disorder-associated ED, such as that linked to diabetes and obesity, elevated circulating inflammatory cytokines, chemokines (e.g., IL-1), and adhesion molecules (ICAM-1, VCAM-1, and P-selectin) play pivotal roles in disease progression." (PMID 41281764, 2025). "ICAM1 plays an important role in autoimmunity and islet rejection, leading to the death and dysfunction of islet β cells and causing the onset of diabetes." (PMID 39199149, 2024). "Together, this indicates that elevated TRLs are associated with increased endothelial cell ICAM1 expression, allowing for increased monocyte recruitment, which mediates some of the deleterious effects of diabetes on the glomerulus." (PMID 38743496, 2024). "Diabetes, an HF risk factor, includes increased inflammation, driven by elevated interleukin (IL-1β, IL-6), intercellular adhesion molecule-1 (ICAM-1), and vascular cell adhesion molecule-1 (VCAM-1), and decreased activity of the collagen-degrading MMP." (PMID 37900404, 2023). "Our results also showed that diabetes induction caused a significant increase (male: p < 0.0001, female: p < 0.001) in ICAM1 gene expression in male group in compared to male NDC animals." (PMID 36755074, 2023). "Changes in ICAM-1 serum concentration were reported in ischemic stroke patients with cerebral microbleeds and were associated with increased risk of hypertension and diabetes." (PMID 36277770, 2022). "Treating the animals with the calpain inhibitor, A705232, protected against the diabetes-induced expression of ICAM-1 and prevented the loss of PAR-1 in aortic endothelial cells in situ." (PMID 33258989, 2020). "This is relevant since ICAM-1 over-expression has been associated with diabetic retinal leukostasis and vascular leakage in a rat model of streptozotocin-induced diabetes." (PMID 33291318, 2020). "We investigated the association between the rs5498 (K469E) polymorphism of the ICAM-1 gene and the progression of carotid atherosclerosis in subjects with type 2 diabetes mellitus (T2DM)." (PMID 27090396, 2016). "Many studies illustrated associations between ICAM-1 K469E polymorphism and peripheral occlusive arterial disease, inflammatory bowel disease, coronary artery disease, diabetes mellitus, and endometriosis." (PMID 24591755, 2014). "We aim to investigate the effects of curcumin on preventing diabetes-induced vascular inflammation in association with its actions on Txnip, ICAM-1, and NOX2 enzyme expressions." (PMID 25054130, 2014). "In this study, mRNA levels of IL-1β, IL-6 and ICAM-1 were increased in the retinas of type 2 diabetic rats after 2 months of diabetes supporting the notion that chronic inflammation underlies the vascular pathology in type 2 diabetes." (PMID 23383097, 2013). "In this study we confirm that diabetes-induced increases in ROS production are associated with an increase in ICAM1 expression." (PMID 24358357, 2013). "In summary, our findings suggest that sST2 levels associate more strongly with predictors of diabetes (triglycerides, glucose, ICAM-1, ALT, GGT), than with established cardiovascular risk predictors or surrogate vascular markers of atheroma (c-IMT or plaque)." (PMID 23112853, 2012). "Genetic and biological studies have implicated that ICAM1 plays a role in the development of diabetes and DN." (PMID 23346076, 2012). "In the recent years, accumulating reports have implicated that genetic polymorphisms in the ICAM1 gene are associated with diabetes and diabetic nephropathy." (PMID 23346076, 2012). "Soluble ICAM-1 (sICAM-1) is an endothelium-derived inflammatory marker that has been associated with diverse conditions such as myocardial infarction, diabetes, stroke, and malaria." (PMID 21533024, 2011). "The effect is associated with downregulation of retinal VEGF mRNA and ICAM-1 expression and a reduction in the loss of retinal occludin induced by diabetes." (PMID 21139695, 2010).